CRP (C-reactive protein)
Diseases named in the same sentence as CRP in open-access papers (continued):
Sharing a sentence is not in itself a finding about the gene and the disease.
periodontitis (continued). "Additionally, there is a link between the type of periodontitis treatment in periodontitis patients and the reduction of the production of the cardiovascular risk mediators such as C-reactive protein (CRP)." (PMID 39516514, 2024). "The aim of this study was to determine whether CRP/BMI are associated with periodontitis using data from the National Health and Nutrition Examination Survey (NHANES) database." (PMID 37481511, 2023). "Periodontitis is associated with increased IL-6 and CRP levels." (PMID 37239434, 2023). "While CRP serum levels are routinely used to indicate systemic inflammation and nonsurgical periodontal treatment consistently lead to reduced serum CRP levels, less is known about the causal role of inflammation markers in general, and CRP in specific, in the pathogenesis of periodontitis." (PMID 37342352, 2023). "CRP is an acute-phase reactant protein that could be applied as a potential diagnostic tool for gingivitis and periodontitis." (PMID 37102937, 2023). "Elevated CRP level is closely associated with the onset of periodontitis." (PMID 37645411, 2023). "However, associated with altered oxidative stress status, the primary risk factor for CVD in patients with periodontitis appears to be determined by increased CRP levels." (PMID 37214190, 2023). "First, due to its cross-sectional design, this study was unable to establish a causal link between CRP levels and periodontitis in the obese group; therefore, we might choose to begin our next study from this point." (PMID 37481511, 2023). "Genetically proxied IL-6 signaling downregulation was associated with a reduced odds of periodontitis (OR per 1-unit decrement in log-CRP levels = 0.81; 95% confidence interval (CI): [0.66; 0.99]; P = 0.0497) in the inverse variance weighted (multiplicative random effects) regression." (PMID 37342352, 2023). "Therefore, we investigated the roles of IL-6 -572 C/G, CRP -757 A/G, and CRP -717 T/C gene polymorphisms; IL-6 levels; and CRP levels on the occurrence of chronic periodontitis related to CAD patients." (PMID 37239434, 2023). "Therefore, the aim of this study was to evaluate the potential association between CRP/BMI (exposure) and the development of periodontitis by using NHANES data (2009–2010)." (PMID 37481511, 2023). "Additionally, increased CRP levels in adults and pregnant women have been associated to periodontitis." (PMID 38077410, 2023). "This increase in IL-6 is strongly correlated with the presence of C-reactive protein and may be closely linked to oral parameters of patients with periodontitis, such as increased probing pocket depth and number of teeth." (PMID 37026605, 2023). "In conclusion, genetically proxied downregulation of IL-6 signaling was associated with lower odds of periodontitis and CRP might be a causal target for the effect of IL-6 on the risk of periodontitis." (PMID 37342352, 2023). "In addition, various biochemical risk markers for CVD were more frequently elevated in periodontitis compared to controls (e.g., total cholesterol, triglycerides, C-reactive protein)." (PMID 36794206, 2022). "Untreated periodontitis associated with elevated serum NE and CRP may thereby contribute to the risk for CVD and COPD." (PMID 35683571, 2022). "A common associated factor between periodontitis and cancer is elevated level of hs-CRP." (PMID 35994451, 2022). "CRP and fibrinogen levels are reportedly higher in patients with chronic and aggressive periodontitis than in healthy participants, and tooth loss is associated with increased fibrinogen and factor VIII levels, supporting this hypothesis." (PMID 36675681, 2022). "Furthermore, the observational nature of the study impairs the conclusion of causality, thus robust evidence has been reported regarding periodontitis increasing circulating levels of CRP and hs-CRP42." (PMID 35418117, 2022). "However, CRP has been established as a marker of association of periodontitis with other systemic diseases." (PMID 34394107, 2021).
periodontitis (continued). "CRP is regarded as one of the risk factors for chronic periodontitis." (PMID 33832490, 2021). "The association between periodontitis and an increase of serum CRP has been reported elsewhere." (PMID 33603787, 2021). "The relationships among the weighted genetic CRP score, which combines serum CRP levels and single-nucleotide polymorphisms previously identified through genome-wide association studies as robustly associated with serum CRP, periodontitis, and NAFLD, were investigated." (PMID 33918456, 2021). "Furthermore, it was found that ACVD is associated with more severe periodontitis and this was marked by higher serum level of high sensitivity (hs)-CRP." (PMID 33521070, 2020). "However, additional studies, in particular intervention and longitudinal studies, with special attention to confounding factors, are needed to further assess the association between periodontitis and serum levels of CRP." (PMID 32994872, 2020). "Cases of very progressive and extensive periodontitis are associated with higher CRP levels." (PMID 32994872, 2020). "Shrihari affirms that periodontitis determines a status of LGI with a slight increase in CRP levels and, consequently, it may be an indirect risk factor for cardiovascular diseases." (PMID 32486269, 2020). "Furthermore, the rs1333048 polymorphism within ANRIL has been associated with higher plasma levels of C reactive protein (CRP) in patients with periodontitis." (PMID 32346660, 2020). "Follow-up data of 2.714 participants spanning five years from the cohort of Study of Health in Pomerania (SHIP), a population-based prospective cohort study in the northeast region of Germany, were analyzed for anthropometric measures, periodontitis, tooth loss, CRP and IL-6." (PMID 32486269, 2020). "Interestingly, a pilot study identified that a genetic variant in the CDKN2B-AS1 locus was associated with the extent of elevated levels of C-reactive protein in periodontitis." (PMID 32489774, 2020). "Therefore, the objective of this study was to evaluate the association between periodontitis and serum levels of CRP." (PMID 32994872, 2020). "Therefore, age is a confounding factor that should be evaluated in studies in which the association between periodontitis and serum CRP levels is assessed." (PMID 32994872, 2020). "Furthermore, periodontitis has been associated with higher serum levels of different inflammatory biomarkers, such as interleukin 6, prostaglandin, and C-reactive protein (CRP)." (PMID 31805680, 2019). "The systemic condition of the patients included in this study may have predisposed them to periodontitis progression, as our results demonstrated that factors such as the activity of eRA (assessed by hs-CRP) were associated with CAL progression." (PMID 31703715, 2019). "Moreover, periodontitis has been positively associated with higher serum levels of different inflammatory biomarkers, such as interleukin 6 (IL-6), IL-17, C-reactive protein, and prostaglandins." (PMID 31817129, 2019). "Additionally, the serum IL-6 and CRP levels have a positive association with the extent of periodontitis." (PMID 29980169, 2018). "CRP is a sensitive marker of systemic inflammation, and periodontitis may be associated with an increase in CRP levels." (PMID 29439734, 2018). "Increased serum NE and CRP caused by periodontitis may link periodontal and systemic diseases [cardiovascular disease (CVD), ischemic stroke, as well as chronic obstructive pulmonary diseases (COPD)]." (PMID 29484548, 2018). "Untreated periodontitis is associated with elevated NE and CRP and thus may contribute to the risk for CVD and COPD." (PMID 29484548, 2018). "Elevated serum CRP is associated with both periodontitis and T2DM." (PMID 28431542, 2017). "Serum blood CRP could be one of the plausible inflammatory biomarkers in the association between periodontitis and APO." (PMID 29017560, 2017).
periodontitis (continued). "The antibody response to periodontopathic bacteria and levels of CRP could be associated with MS and periodontitis." (PMID 26871443, 2016). "Periodontitis has been shown to be associated with a raised serum pro-inflammatory state as shown by increases in C Reactive Protein (CRP) and pro-inflammatory cytokines (e.g. Tumour Necrosis Factor α (TNFα)) with a reduction in anti-inflammatory markers (e.g. interleukin 10 (IL 10))." (PMID 26963387, 2016). "We thought that an altered IgG antibody response to A. actinomycetemcomitans and CRP may play a role in the association of MS and severe periodontitis in this group of the Thai population." (PMID 26871443, 2016). "Additionally, the levels of CRP, previously reported to be associated with periodontitis and with anti-P." (PMID 27809921, 2016). "Data from the National Health and Nutrition Examination Survey show that physically active adults have a lower risk of periodontitis, and adults with periodontitis had elevated levels of C-reactive protein and white blood cell counts in the gingival crevicular fluid." (PMID 23537519, 2013). "Subjects with severe periodontitis and high levels of mean clinical attachment loss (3.78 mm) had significantly higher mean CRP levels (8.25±9.35 mol/L) than subjects with moderate periodontitis and lower levels of mean clinical attachment loss (2.05±0.53 mm) and mean CRP levels (4.93±3.23 mol/L)." (PMID 23019501, 2011). "The prevalence of CVD appears to be highest in patients with periodontitis and co-existing elevated CRP levels, suggesting that periodontitis might increase the risk of vascular disease through activating the systemic inflammatory and immune responses." (PMID 19018303, 2008). "Notably, while CRP accounted for the largest proportion of mediation among the inflammatory biomarkers examined, it explained only 8.1% of the total association between DI-GM and periodontitis, suggesting a modest contribution." (PMID 40880748, 2025). "Thus, we were limited in examining the concomitant medications, underlying medical conditions, and/or periodontitis treatments that could be major confounders between periodontitis and CRP levels." (PMID 39453923, 2024). "However, in patients with periodontitis, local proinflammatory cytokines and transient bacteremia overexpression may be associated with increased oxidative stress and CRP levels." (PMID 37711554, 2023). "While our analyses suggest a causal role of CRP in the pathogenesis of periodontitis, this finding was rather unexpected, and it remains to be seen whether CRP is a suitable target to break the vicious feed-forward loop linking periodontitis to systemic low-grade inflammation." (PMID 37342352, 2023). "Besides, research on the association between low bone mineral density and periodontitis in perimenopausal women, the association between homocysteine, C-reactive protein, lipid levels, and sleep quality in perimenopausal and postmenopausal women, and so on are frontiers in subsequent research." (PMID 36164290, 2022). "Moreover, higher CRP and IL-6 levels may be found in patients affected by periodontitis and an association between IL-6 levels, and the extent of periodontitis has been demonstrated." (PMID 35996409, 2022). "Systemic inflammatory disease states associated with periodontal disease are hypothesized to occur due to transmigration of periodontal pathogens and/or periodontitis-associated inflammatory mediators, such as IL-1, IL-6, CRP, and fibrinogen in the bloodstream." (PMID 34950607, 2021). "Furthermore, periodontitis has been associated with high CRP plasma levels." (PMID 28403353, 2017). "Thus, even though an association between periodontitis and elevated risk factors (CRP) for CVD were observed with the presence of periodontal microorganisms, further studies are needed to confirm the possible role of specific harmful microorgamisms in the association observed." (PMID 23019501, 2011).
periodontitis (continued). "CRP could amplify the inflammatory response through complement activation, tissue damage, and induction of inflammatory cytokines in monocytes, and therefore, may mediate the association between periodontitis and adverse pregnancy outcomes." (PMID 20379412, 2009). "Therefore, CRP might be a plausible mediator of the association between periodontitis and adverse pregnancy outcomes." (PMID 20379412, 2009). "Periodontitis is further characterized by elevated serum levels of C-reactive protein (CRP) and by a reduction in anti-inflammatory markers like interleukin (IL)-10." (PMID 40600213, 2025). "Epidemiological studies have reported that serum CRP levels are elevated in patients suffering from chronic periodontitis." (PMID 40076898, 2025). "Multiple studies have also observed signs of systemic inflammation in HD patients with periodontitis, with elevated levels of CRP, amongst other inflammatory biomarkers such as IL‐6 and IL‐8." (PMID 41476846, 2025). "Periodontitis was significantly associated with HNC (HR 5.99 [1.96–18.30]), while elevated CRP (>15 mg/L) independently increased risk (HR 4.16 [1.45–12.00])." (PMID 40076898, 2025). "It is plausible that the mechanism of CRP induction is similar in peri-implantitis and periodontitis, with potential systemic implications." (PMID 41301163, 2025). "Beyond bacterial pathogens, the characteristic systemic low-grade inflammatory state of periodontitis elevates circulating levels of C-reactive protein, IL-6 and TNF-α, representing another crucial pathway linking periodontitis to NAFLD." (PMID 40951429, 2025). "To further characterize the periodontitis status, we analyzed the serum high-sensitivity C-reactive protein (hs-CRP) and growth differentiation factor-15 (GDF15) levels." (PMID 40351551, 2025). "Patients with periodontitis also exhibit elevated serum levels of IL-6 and CRP, with IL-6 levels correlating with the severity of the disease." (PMID 39852378, 2025). "Several innovative techniques have been developed to diagnose periodontitis based on CRP (C-reactive protein) levels and other biomarkers." (PMID 41440361, 2025). "Next, RF, SVM and GB were employed incorporating a set of systemic parameters (including serum CRP and lipid profiles) to predict the diagnosis of periodontitis." (PMID 40701837, 2025). "This points to the potential of CRP to serve as a predictor of periodontitis due to its role as an acute-phase reactant that responds to bacterial components involved in periodontal infection, such as Porphyromonas gingivalis and Treponema denticola." (PMID 39859455, 2025). "The study’s findings indicated the emergence of elevated CRP and low eGFR as predictor biomarkers for periodontitis." (PMID 39859455, 2025). "The local inflammation is represented by TNF-α, while the systemic inflammation that increases with the onset and progression of chronic periodontitis is represented by hs-CRP." (PMID 41466021, 2025). "For instance, increased systemic inflammatory markers, such as C-reactive protein (CRP) and IL-6, are commonly elevated in both periodontitis and these systemic conditions, suggesting shared pathological mechanisms." (PMID 40066344, 2025). "This inflammatory state is exacerbated by elevated levels of pro-inflammatory markers, such as C-reactive protein (CRP), tumor necrosis factor-alpha (TNF-α), and interleukin-6 (IL-6), commonly associated with both periodontitis and cardiovascular diseases." (PMID 40066344, 2025). "Low-grade inflammation e.g. serum IL-6 and C-reactive protein (CRP) was associated with kidney function decline, and thus is of relevance to periodontitis." (PMID 40421989, 2025). "Blood: Systemic inflammatory markers such as CRP, IL-6, and advanced glycation end products (AGEs) are elevated in patients with severe periodontitis." (PMID 40418274, 2025).
periodontitis (continued). "Specifically, our mediation analysis highlighted the pivotal roles of systemic inflammatory biomarkers, particularly CRP and WBC count, in explaining the inverse association between DI-GM scores and periodontitis prevalence." (PMID 40880748, 2025). "Conversely, diagnosis of periodontitis was predicted using modelling of the common biomarkers of health (CRP, LDL, HDL, TG, TC) as well as demographic (age, gender, ethnicity) and lifestyle variables (smoking habits, BMI)." (PMID 40701837, 2025). "Periodontitis triggers a robust immune response, including elevated pro-inflammatory cytokines, increased serum C-reactive protein (CRP), and reduced anti-inflammatory markers such as interleukin-10." (PMID 40038641, 2025). "Longitudinal studies indicate that periodontitis accelerates the progression of cardiovascular disease by elevating levels of certain systemic inflammatory markers, such as CRP." (PMID 40703374, 2025). "For instance, oral inflammation, particularly gingivitis and periodontitis, can significantly elevate CRP concentrations via the gingival crevicular fluid, even in the absence of systemic disease." (PMID 40871545, 2025). "Chronic periodontitis leads to the production of a significant amount of circulating pro-inflammatory mediators (IL-1β, IL-6, TNFα), C-reactive protein (CRP), etc.." (PMID 40491910, 2025). "The population we analyzed was typical of patients with chronic periodontitis, as evidenced by clinical indicators and CRP levels." (PMID 40351551, 2025). "Elevated CRP (>15 mg/L) and reduced eGFR (<60 mL/min/1.73 m2) were significant predictors of periodontitis, with hazard ratios (HR) of 1.36 [1.05–1.77] and 1.39 [1.08–1.78], respectively." (PMID 39859455, 2025). "Beyond its local effects, periodontitis contributes to systemic inflammation, evidenced by elevated systemic markers like C-reactive protein (CRP)." (PMID 41333482, 2025). "Patients with periodontitis had a mean CRP level of 39.30 (SD = 62.84), based on 10,039 available outcomes, whereas patients without periodontitis had a mean CRP level of 35.79 (SD = 59.57) from 7,110 outcomes." (PMID 41420778, 2025). "There is strong evidence from cross-sectional studies that plasma CRP levels are elevated in patients with periodontitis compared with control groups, with many studies reporting CRP levels > 2.1 mg/L." (PMID 40572711, 2025). "A t-test comparing the two cohorts resulted in a test statistic of 3.684 with 17,147 degrees of freedom and a p-value of less than 0.001, indicating that the CRP levels were significantly higher in patients with periodontitis." (PMID 41420778, 2025). "Our findings extend these observations, demonstrating that lower DI-GM scores, are positively correlated with both higher CRP concentrations and increased periodontitis prevalence." (PMID 40880748, 2025). "Individuals with periodontitis often show elevated leukocyte counts and heightened levels of systemic inflammatory markers, such as C-reactive protein." (PMID 40283848, 2025). "Mediation analysis showed that TG, HDL-C, ALB, UA, CRP, WBC, and neutrophil count significantly mediated the association of CircS with periodontitis." (PMID 40672423, 2025). "Subsequently, elevated levels of systemic inflammatory markers, particularly CRP and WBC, were significantly associated with increased prevalence of periodontitis, whereas higher PLR levels correlated inversely with periodontitis prevalence." (PMID 40880748, 2025). "Numerous studies have reported increased circulating levels of C-reactive protein (CRP) in patients suffering from severe periodontitis." (PMID 41010819, 2025). "Periodontitis independently changes the serum levels of leptin, adiponectin, and C-reactive protein (CRP)." (PMID 40243433, 2025).